HPSE (heparanase)
Diseases named in the same sentence as HPSE in open-access papers (continued):
Sharing a sentence is not in itself a finding about the gene and the disease.
tumor (continued). "The heparanase-mediated cleavage of HS is best studied in the context of malignant tumor progression, where the enzyme has been shown to promote tumor growth and therapy resistance through multiple mechanisms." (PMID 36979689, 2023). "Aberrant heparanase-1 expression is correlated with inflammation, tumor angiogenesis, metastasis, tumor aggressiveness, and poor prognosis." (PMID 36680276, 2023). "This was supplemented by a study that showed successful inhibition of tumor cell migration, invasion and adhesion by a polymer-based heparin molecule via inhibition of Heparanase activity." (PMID 36986571, 2023). "In fact, much of the impact of heparanase on tumor progression is related to its function in mediating tumor–host crosstalk, priming the tumor microenvironment to better support tumor growth, metastasis, and chemoresistance." (PMID 36980232, 2023). "PI-88 is another heparanase inhibitor used in animal models that reduced tumor growth in 13762 MAT cells by inhibiting metastasis and tumoral angiogenesis." (PMID 37759706, 2023). "Heparanase is a multitasking protein whose activation promotes, among other effects, the release of various cytokines, chemokines and growth factors in the tumor microenvironment." (PMID 36980254, 2023). "New discoveries have led to the consideration of a possible role for HPSE in modulating autophagy, mainly in the context of tumor growth and chemoresistance, although such a function still remains to be elucidated." (PMID 37508554, 2023). "In this way, heparanase mediates tumor‐host crosstalk and promotes basic cellular processes that together orchestrate tissue remodeling." (PMID 37547889, 2023). "Much of the impact of heparanase on tumor progression is related to its function in mediating tumor‐host crosstalk, priming the tumor microenvironment to better support tumor growth, metastasis, and chemoresistance." (PMID 37547889, 2023). "Heparanase is an enzyme that degrades heparan sulfate and serves as a master regulator of the aggressive tumor phenotype and crosstalk within the tumor microenvironment." (PMID 37091070, 2023). "Heparanase regulates multiple biological activities in cancers, e.g., enhancing tumor growth, angiogenesis, and metastasis." (PMID 36980232, 2023). "Nuclear heparanase enhances chromatin remodeling, stimulates gene transcription involved in MM progression, and blocks the tumor suppressor function of PTEN." (PMID 36980254, 2023). "Heparanase-2 appears to function as a natural inhibitor of the heparanase enzyme and a tumor suppressor." (PMID 36980254, 2023). "Pixatimod (PG545) is a synthetic HS mimetic and a strong heparanase-1 inhibitor with anti-cancer properties (inhibitor of angiogenesis, tumor growth and metastasis)." (PMID 36680276, 2023). "There is ample evidence to indicate a correlation between heparanase-1 activity and the metastatic potential of tumor cells." (PMID 36680276, 2023). "Targeting heparanase exerts not only direct anti-tumor effects but protects against radiation-induced kidney damage—the backbone of cancer therapy across a range of malignancies." (PMID 36979689, 2023). "The current literature reports an increase in HPSE expression leading to increased angiogenesis that in turn correlates with an increased tumour size and growth rate in numerous cancer settings." (PMID 37297024, 2023). "Exacerbated remodeling of the ECM by heparanase-1 is observed in the early stages in cancer (tumorigenesis), but also in late phases (i.e., tumor invasion and metastasis)." (PMID 36680276, 2023). "Due to the presence of heparin shell, the nanorods are in the anionic state during delivery, while heparanase, an effective promoter of tumor microenvironment, is specifically expressed in most tumor cells." (PMID 36765624, 2023). "Heparin mimetics have antitumor activity due to their ability to inhibit heparanase and endoglycosidase (these enzymes promote tumor cell spread) and suppress angiogenesis by binding growth factors." (PMID 36297616, 2022).
tumor (continued). "In disease states, however, elevated HPSE expression is observed, most notably in cancer where it is involved in multiple important roles including extracellular remodelling, tumour angiogenesis, and metastasis." (PMID 36291066, 2022). "To validate the HPSE expression distribution in the tumor immune microenvironment, we further generated a transcriptional map of immune cells in human ESCC." (PMID 35840985, 2022). "The antibiosis of this fungus shows that its metabolite trachyspic acid can inhibit the tumor cell heparanase." (PMID 35161236, 2022). "Such architecture allows heparanase-mediated tumor-host crosstalk and promotes several basic cellular processes (i.e., exosome formation, autophagy, immune-inflammatory responses) that together coordinate tissue remodeling." (PMID 35970822, 2022). "Decreased heparanase (HPSE) mRNA expression reduces the anti-tumor function of CAR-T cells in solid tumors because HPSE aids in the penetration of HSPGs, which in turn increases the abundance of the ECM." (PMID 35326556, 2022). "Release of HS side chains is thought to increase the pro-tumorigenic effects of heparanase promoting tumor invasion." (PMID 36428962, 2022). "Heparanase aids tumor invasion by shattering the ECM, releasing angiogenic factors, and recruiting an angiogenic environment." (PMID 36340029, 2022). "Mice transplanted with bone marrow-derived from heparanase-overexpressing transgenic mice show enhanced tumour aggressiveness and shorter survival times." (PMID 34982945, 2022). "Heparanase also regulates inflammation-related genes transcription and inflammatory cell extravasation, and accelerates primary tumor growth." (PMID 36139645, 2022). "It is well documented that HPSE activity is involved in glomerular basement membrane disassembly and proteinuria in several glomerulopathies and in angiogenesis and tumor cell migration in cancer progression." (PMID 35329997, 2022). "The results indicate that HPSE is likely to be mainly expressed on tumor cells and monocytes in the immune microenvironment." (PMID 35840985, 2022). "As a proof of concept, it has been shown that heparanase overexpression in transgenic mice (Hpa-Tg) makes the tumor microenvironment more conducive to neoplastic development in various experimental models of in vivo tumorigenesis." (PMID 35965510, 2022). "In summary, stage II tumor tissue presented an increase in heparanase and IL-4R, while stage II non-tumor adjacent tissue presented an increase in VEGF-B and the pIκB/IκB ratio." (PMID 36139645, 2022). "Especially since heparanase expression is highly relevant to cancer metastasis, does heparanase degradation of heparin in mast cells have an impact on the functions of mast cells in tumor metastasis?" (PMID 35563215, 2022). "Through in vitro and in vivo experiments, this work revealed the function of HPSE in tumor development by regulating the cell cycle via the AKT/p27Kip1 pathway." (PMID 36130926, 2022). "By cleaving heparan sulfate, heparanase contributes to the regulation of numerous physiological and pathological processes such as wound healing, inflammation, tumour angiogenesis, and cell migration." (PMID 36291066, 2022). "We also analyzed the expression of HPSE in immune cells by single-cell sequencing and observed HPSE expression in both tumor tissues and para-cancerous tissue-resident immune cells." (PMID 35840985, 2022). "Further, silencing of HPSE or treatment of tumor with compounds that block HPSE activity is shown to remarkably attenuate tumor progression." (PMID 36157032, 2022). "Preclinical trials have shown that blocking heparanase with inhibitors, developed as antineoplastic agents, significantly diminishes tumor growth and metastasis." (PMID 36428962, 2022). "When codelivered therapeutic agents nanoplatforms enter the tumor microenvironment, overexpressed heparanase-1 can rapidly recognize the outer heparin shell and cleave it, resulting in the release of cargoes for tumor cell kill." (PMID 36096856, 2022).
tumor (continued). "In turn, elevated estrogen levels further promoted heparanase production by ER-positive tumor cells, which contributed to the acquisition of a tumor-promoting phenotype of tumor-associated macrophages." (PMID 36074318, 2022). "Heparanase functions as an “activator” of HS proteoglycans and therefore is a pivotal player in creating a supportive environment for tumor cell proliferation and dissemination." (PMID 35970822, 2022). "Of interest is that HPSE expression is elevated virtually in all major types of cancers, and this up-regulation is positively correlated with metastatic potential of tumor and poor prognosis, which makes HPSE a valuable therapeutic target." (PMID 36157032, 2022). "Tumour cells secrete a large amount of heparanase to destroy the strong network structure of the extracellular matrix and basement membrane, promoting the invasion of inflammatory cells and metastasis of tumour cells and the progression of related diseases." (PMID 35643506, 2022). "As a degrading enzyme, HPSE is involved in biological and pathological processes, including tissue repair, inflammation, tumor angiogenesis, invasion, and metastasis." (PMID 35840985, 2022). "Gleditsiae Spina mainly downregulates the expression of heparanase and β-catenin to affect the composition of tumor cytoplasmic matrix and can regulate the PI3K-AKT pathway, integrating multiple targets and multiple pathways to play a therapeutic role." (PMID 35299895, 2022). "Among the GAGs, HS, when cleaved by heparanase, alters its structure and function, and contributes to tumor-mediated remodeling of both cell surfaces and the ECM." (PMID 36452484, 2022). "HPSE, the only mammalian endoglycosidase that cleaves HS, contributes to tumor angiogenesis, growth, metastasis, chemoresistance, and poor prognosis in multiple tumors." (PMID 34461608, 2021). "HPSE is required for macrophage activation, crosstalk with the tumor microenvironment, and tumorigenesis; the mechanism involves HPSE-mediated TLR activation at the cell membrane, followed by Erk/p38/JNK activation and AP1-mediated transcription." (PMID 34461608, 2021). "Various levels (on an intensity score of 1 to 3+) of heparanase staining by IHC in tumor cells were detected in 220 out of 641 samples (35%)." (PMID 34050190, 2021). "Heparanase can destroy the extracellular matrix and is involved in tumor metastasis and angiogenic activity." (PMID 34220326, 2021). "Targeting heparan sulfate proteoglycans, as a member of extracellular matrix (ECM) which limits cells homing to the tumors, with heparanase (HPSE)-expressing CARs also overcomes the physical barrier and improves CARs infiltration to the tumor." (PMID 33522929, 2021). "Heparanase can be double-edged; as a promoter of tumor survival and growth, heparanase can also enhance tumor immune surveillance and tumor cell clearance." (PMID 34715781, 2021). "Glycolytic enzymes such as HPSE and HYALs, demonstrate unique roles in tumor progression, through HS and HA cleavage, respectively, thus modulating invasive and angiogenic events." (PMID 33809973, 2021). "Following HPSE overexpression in tumor-derived cells increase in autophagy is observed, while also rendering them more resistant to stress cues and chemotherapy." (PMID 33809973, 2021). "A great body of evidence indicates that tumour sensitivity to drug treatment is affected by glycosylation, particularly by altered expression of cell-surface HSPGs and/or HPSE." (PMID 33494442, 2021). "The overexpression of heparanase results in vivo in increased tumor metastasis, whereas downregulating heparanase markedly decreases cancer cells’ ability to metastasize." (PMID 33800172, 2021). "After indicating that heparanase increase ER+ tumor cell survival following chemotherapy, we sought to investigate the molecular mechanisms behind this role." (PMID 34050190, 2021).
tumor (continued). "A deregulated heparanase/HSPG system profoundly impacts on tumor aggressiveness by acting both in the tumor microenvironment and inside the tumor cells." (PMID 34857011, 2021). "Studies provide compelling evidence that ties heparanase levels with all steps of tumor formation including tumor initiation, growth, metastasis, and chemoresistance." (PMID 35069219, 2021). "Considering the upregulation of HPSE in most cancers, its unique role in HS degradation and involvement in tumor progression, it is sensible to view it as an attractive target for the development of cancer therapies." (PMID 33809973, 2021). "Herein, these studies indicate that Salmonella inhibits the protein expression of heparanase in tumor cells." (PMID 34220326, 2021). "Then, we further detected HPSE protein expression levels in the tumors of 88 HCC patients using IHC staining, and confirmed that the average HPSE IHC score in tumor tissues was significantly higher than that in peritumor tissues." (PMID 33597510, 2021). "By entering the nucleus and degrading nuclear syndecan-1, heparanase mediates HAT activation and transcription of genes associated with an aggressive tumor phenotype." (PMID 34681753, 2021). "The authors claim that most of the patients whose tumours were characterised by higher levels of heparanase were treated with tamoxifen." (PMID 34070058, 2021). "Perlecan has been proposed as a molecular switch, acting initially to deter tumour development, but when it is modified by MMPs and heparanase it can be transformed into a tumour-tolerant matrix component." (PMID 33922532, 2021). "It is well-documented that heparanase overexpression occurs in most malignancies and is involved in tumor progression and prognosis." (PMID 34681753, 2021). "HPSE has functions that are related to its enzymatic activity including tumor metastasis, angiogenesis, embryo implantation, wound healing, inflammation, and autoimmunity." (PMID 34578329, 2021). "Bioinformatics analysis of these differential genes suggested that heparanase allows tumor progression through different mechanisms, including dedifferentiation, luminal progenitors regulation, and EMT induction." (PMID 34050190, 2021). "Treatment with an increased amount of Salmonella significantly downregulated the expression of heparanase in the two types of tumor cells." (PMID 34220326, 2021). "The tumor cells can release heparanase and digest extracellular matrixes to help cell migration to distant sites." (PMID 34220326, 2021). "Heparanase activity can influence several biological and pathological processes, including tissue repair, inflammation, tumor angiogenesis, invasion, and metastasis." (PMID 33411145, 2021). "The heparanase inhibitor roneparstat was used to show that inhibiting heparanase activity was crucial for delaying tumor relapse in mice." (PMID 34249755, 2021). "An essential mechanism of heparanase action is promoting exosome secretion, which affects both tumor and host cells’ biological behavior and finally drives tumor progression." (PMID 33800172, 2021). "In pre-clinical in vivo mouse models of MPM, the dependency on heparanase for tumor growth was demonstrated in the context of heparanase gene disruption and in response to heparanase-inhibiting compounds." (PMID 35069219, 2021). "It is reported that overexpression of heparanase also stimulates the phosphorylation of EGFR in different tumor cell lines and inhibiting heparanase expression results in the reduction of EGFR phosphorylation." (PMID 34681753, 2021). "Heparanase, the sole heparan sulfate degrading endoglycosidase, regulates multiple biological activities that enhance tumor growth, angiogenesis and metastasis." (PMID 35069219, 2021). "Degradation of nuclear Sdc-1 by heparanase enhances histone acetyltransferase activity and promotes expression of genes that aggressively drive the attainment of a tumour phenotype." (PMID 33922532, 2021).
tumor (continued). "In this study, we have demonstrated that a new triazole–thiadiazole-bearing small molecule showed good heparanase inhibition along with attenuation of tumor growth and metastasis." (PMID 34199150, 2021). "In this study, multi-database integration analysis indicated that high HPSE expression contributes to macrophage M2 polarization and T cell exhaustion, thus promoting tumor growth." (PMID 34461608, 2021). "Here, heparanase contributes to the regulation of tumor-related processes, such as angiogenesis, inflammation, and tumor cell invasion and metastasis, reviewed in detail recently." (PMID 34681753, 2021). "Heparanase-mediated degradation of heparan sulfate (HS) is the critical process for tumor angiogenesis and metastasis, and heparanase has thus become an attractive target for cancer research." (PMID 33803892, 2021). "HPSE is upregulated in many types of human tumors, and this elevation contributes to tumor angiogenesis, growth, metastasis, chemoresistance, and poor prognosis." (PMID 34461608, 2021). "Compelling evidence gathered during the last two decades tie heparanase levels not only with tumor metastasis but with all steps of tumor development, including tumor initiation, angiogenesis, growth, metastasis, and chemoresistance." (PMID 34199150, 2021). "Consistent with the downregulation of heparanase expression, the tumor migration behavior was inhibited." (PMID 34220326, 2021). "The results of our study indicate that Salmonella plays a vital role in the inhibition of tumor metastasis through the downregulation of heparanase." (PMID 34220326, 2021). "Heparanase has the ability to modify the expression of genes involved in these tumor-related processes including IL-17A, MCP-1, MMPs, TNF-α, VEGF, and VEGF-C." (PMID 34681753, 2021). "One study demonstrated that both murine and human NK cells express heparanase upon activation, which was necessary for tumor invasion and prevention of metastases." (PMID 34917099, 2021). "HPSE has been also suggested as a key regulator of the tumor microenvironment and tumor progression." (PMID 34461608, 2021). "In most tumor types, heparanase was reported to be overexpressed and correlated with increased tumor size, angiogenesis, metastasis and poor prognosis." (PMID 34220822, 2021). "The protein levels of heparanase were inhibited in tumor cells, treated with Salmonella including 4T1 and B16F10 cells (p<0.05 for S.C. MOI=0 versus MOI=200 in 4T1 and B16F10)." (PMID 34220326, 2021). "Because Salmonella can influence the protein levels of heparanase in two types of tumor cells, Salmonella induced the potential signaling pathway in tumor cells." (PMID 34220326, 2021). "On univariate analysis, overweight IBrC subjects and patients with a tumour diameter of ≥2 cm demonstrated a lower chance of a lower pre-treatment heparanase concentration (p = 0.0397, p = 0.0361, respectively)." (PMID 34070058, 2021). "Since inflammatory conditions favor tumor initiation, it is proposed that HPSE is a possible mediator in inflammation-driven cancer." (PMID 33809973, 2021). "Heparanase has been suggested to induce Akt phosphorylation in endothelial cells, macrophages, fibroblasts, and various tumor-derived cells." (PMID 34681753, 2021). "Mechanistically, we found that Salmonella regulated tumor metastasis by downregulating heparanase expression through the AKT/ERK signaling pathway." (PMID 34220326, 2021). "HPSE is able to change the function of HSPGs in the tumour microenvironment and is a regulator of several cancer hallmarks, namely, angiogenesis and the development of metastasis." (PMID 33494442, 2021). "Depending on the tumour diameter, significantly higher pre- (p = 0.0281) and post-treatment (p = 0.0128) concentrations of heparanase were obtained in patients with T2 tumours (≥2 cm) with respect to T1 (<2 cm)." (PMID 34070058, 2021).